CYP2E1 (cytochrome P450 family 2 subfamily E member 1)
Diseases named in the same sentence as CYP2E1 in open-access papers (continued):
Sharing a sentence is not in itself a finding about the gene and the disease.
laryngeal carcinoma (2 papers, 2014 to 2016). Carcinoma that arises from the laryngeal epithelium. "Our case-control study showed that the CYP2E1*5 -1293C allele is associated with an increased risk for laryngeal cancer, and is therefore a genetic factor for laryngeal cancer susceptibility." (PMID 25299224, 2014). "In summary, our case-control study showed that genetic polymorphisms of CYP1B1 and CYP2E1 are closely associated with an individual's susceptibility to developing laryngeal cancer." (PMID 25299224, 2014). "Our case-control study of the Han Chinese population revealed that three SNPs at CYP1B1*2 G355T, CYP1B1*2 C4326G, and CYP2E1*5 G-1293C are associated with an individual's susceptibility to laryngeal cancer." (PMID 25299224, 2014). "Environmental factors (smoking and drinking) and genetic factors (CYP1B1*2 355T and CYP2E1*5 -1293C) are both associated with an individual's susceptibility to developing laryngeal cancer (P value for all these evaluations were < 0.001)." (PMID 25299224, 2014). "CYP1B1*2 355T and CYP2E1*5 -1293C are associated with an increased laryngeal cancer risk, while CYP1B1*3 4326G is associated with a decreased risk." (PMID 25299224, 2014). "This study was conducted to explore the effects of genetic polymorphisms (CYP1B1*2 G355T, CYP1B1*3 C4326G, and CYP2E1*5 G-1293C) and environmental factors (smoking and drinking) on susceptibility to laryngeal cancer in a Han Chinese study group." (PMID 25299224, 2014). "Here, we report results of a case-control study investigating the association of three important SNPs of P450 (CYP1B1*2 G355T, CYP1B1*3 C4326G, and CYP2E1*5 G-1293C) and two major environmental factors (smoking and drinking) with susceptibility to laryngeal cancer." (PMID 25299224, 2014). "Our data showed that the joint effects of CYP2E1*5 G-1293C and smoking or drinking on laryngeal cancer risk are not significantly different from the effects of individual genetic or environmental factors." (PMID 25299224, 2014).
leprosy (2 papers, 2012 to 2015). Leprosy is a chronic infectious disease affecting primarily the skin and peripheral nervous system. "Concerning genotypic and allelic distribution of SNPs, a high (42.3%), statistically significant, frequency of the heterozygous genotype for the CYP2E1*6 allele was found among leprosy patients." (PMID 23077626, 2012). "A significant difference was found between healthy individuals and patients for the CYP2E1*6 allele, which is more common among leprosy patients (X2 = 11.6; p = 0.003)." (PMID 23077626, 2012). "Among leprosy patients, CYP2E1*5 allele was more frequent in the LBI group." (PMID 23077626, 2012). "In leprosy patients, the GSTM1*0 and CYP2E1*5 alleles and the combined alleles GSTM1*0/CYP2E1*6 and GSTM1*0/CYP2E1*5 were significantly related to a baciloscopic index (BI) (BI<3), while the CYP2E1*6 allele was related to a better clinical evolution in the leprosy spectrum." (PMID 23077626, 2012). "We investigated the possible effects of CYP2E1 and GSTM1 polymorphisms in 71 leprosy patients and in 110 individuals from the general population." (PMID 23077626, 2012). "Allele and genotype distributions of CYP2E1 and GSTM1 genes within two samples from leprosy patients and healthy individuals." (PMID 23077626, 2012). "Taken together, our results suggest that the CYP2E1*5, CYP2E1*6 and GSTM1*0 alleles may be considered as susceptibility markers for leprosy, and their distribution should be further investigated, as their presence seems to confer protection from M. leprae." (PMID 23077626, 2012). "Therefore, GSTM1*0, CYP2E1*5 and CYP2E1*6 may be possible protection factors for leprosy patients." (PMID 23077626, 2012). "We investigated the possible effects of CYP19A1 [rs11575899], NFKβ1 [rs28362491], IL1α [rs3783553], CASP8 [rs3834129], UGT1A1 [rs8175347], PAR1 [rs11267092], CYP2E1 [INDEL 96pb] and IL4 [rs79071878] genes in a group of 141 leprosy patients and 180 healthy individuals." (PMID 26367014, 2015).
lung adenocarcinoma (2 papers, 2013 to 2022). A carcinoma that arises from the lung and is characterized by the presence of malignant glandular epithelial cells. "Associations between CYP1A1 and lung squamous cell carcinoma (SCC) and associations between CYP2E1 and lung adenocarcinoma (AC) were observed, suggesting a specificity of tobacco smoke PAHs for lung SCC and tobacco-specific nitrosamines for lung AC." (PMID 24069431, 2013). "Lung protein CYP2E1 is related to lung adenocarcinoma, and MMP9 is associated with lung neoplasms." (PMID 35259090, 2022).
lung diseases (2 papers, 2019 to 2023). "A number of these genes have reported associations with COPD or other pulmonary diseases and include; CYP2E1, HEY1, SMAD3, BARD1 and FOXP1." (PMID 31860681, 2019).
neuroblastoma (2 papers, 2012 to 2017). Neuroblastoma (NB) is the most common solid, extracranial childhood tumor. "After ethanol treatment, the CYP2E1 protein and mRNA ethanol induction exhibit greater magnitudes in the neuronal cells than in glial cells, and human neuroblastoma IMR-32 cells show a higher nicotine induced CYP2E1 expression." (PMID 28163821, 2017). "In the present study, we show that AAP activates the neuroblastoma intrinsic apoptotic pathway through a mechanism triggered by an increase in CYP2E1 activity." (PMID 23166834, 2012). "However, in our experiments, co-incubation of neuroblastoma cells with AAP and TTD, a CYP2E1 inhibitor, at a concentration that has been shown to completely inhibit CYP activity in neuroblastoma lysates, only partially prevented AAP-induced neuroblastoma death." (PMID 23166834, 2012).
nicotine dependence (2 papers, 2018 to 2024). Physical and psychological dependence on nicotine. "CYP2E1*1D genotype was also associated with nicotine dependence in FNs, however further studies are needed to elucidate potential mechanisms responsible for this relationship." (PMID 29389890, 2018).
Parkinson’s (2 papers, 2020 to 2022). "Moreover, in the brain of Parkinson’s patients, decreased methylation of the CYP2E1 gene with increased CYP2E1 mRNA levels were observed, suggesting that epigenetic variations of CYP2E1 contribute to PD susceptibility." (PMID 32230811, 2020).
systemic lupus erythematosus (2 papers, 2011 to 2012). An autoimmune multi-organ disease typically associated with vasculopathy and autoantibody production. "Previous studies demonstrated that SNP rs2480256 in the CYP2E1 gene was significantly associated with systemic lupus erythematosus." (PMID 23181071, 2012). "We tried to investigate the possible association of CYP2E1 tag single nucleotide polymorphisms (SNPs) with susceptibility to systemic lupus erythematosus (SLE) in a Chinese Han population." (PMID 21281483, 2011).
thyroid cancer (2 papers, 2020 to 2021). "The pan‐cancer analysis showed that the CYP2E1 expression level was lower in most solid cancers than normal tissues but only upregulated in thyroid carcinoma." (PMID 34612013, 2021).
viral hepatitis (2 papers, 2018 to 2025). An acute or chronic inflammation of the liver parenchyma caused by viruses. "Along with conformational epitopes, our identification of MHC-restricted CYP2E1 epitopes can be used to develop specific diagnostic tests for drug-induced or viral hepatitis or associated fibrosis or to predict individuals at risk for developing these diseases or their sequelae." (PMID 30305319, 2018). "We have found a common MHC-restricted CYP2E1 epitope in anesthetic and viral hepatitis that is a dominant epitope in anesthetic hepatitis and is significantly associated with fibrosis in patients with viral hepatitis." (PMID 30305319, 2018). "Viral hepatitis may modulate acetaminophen metabolism by enhancing the activity of CYP2E1, depleting glutathione reserves, and sensitizing hepatocytes to oxidative injury." (PMID 39917094, 2025). "Our studies highlight a common MHC-restricted CYP2E1 epitope in anesthetic and viral hepatitis with immune and metabolic consequences and strongly suggest that this epitope could be the dominant CYP2E1 epitope in anesthetic hepatitis." (PMID 30305319, 2018). "Hence, we demonstrate a shared CYP2E1 epitope between anesthetic and viral hepatitis." (PMID 30305319, 2018). "Taken together, our report identifies one shared epitope between anesthetic and viral hepatitis that may contribute to sequelae following exposure to drugs or viruses and strongly suggests that this epitope could be the dominant CYP2E1 epitope in anesthetic hepatitis." (PMID 30305319, 2018).
adenomyosis (1 paper, 2025). The growth of endometrial tissue inside the muscular wall of the uterine corpus. "Through bioinformatics analysis, this study identified three key genes closely associated with adenomyosis: LIPH, CYP2E1, and CHRNE." (PMID 40832467, 2025). "To thoroughly investigate potential associations between immune cell infiltration and diagnostic biomarkers in adenomyosis, we systematically analyzed the correlations between 28 immune cell types and three diagnostic markers (LIPH, CYP2E1, and CHRNE)." (PMID 40832467, 2025). "It is hypothesized that CYP2E1 may participate in the pathogenesis of adenomyosis by modulating oxidative stress and inflammatory responses." (PMID 40832467, 2025).
alcoholic pancreatitis (1 paper, 2015). Acute or chronic inflammation of the pancreas due to excessive alcohol drinking. "Nevertheless, a study of CYP2E1 intron 6 Dra I polymorphism showed a weak positive association of DD genotype to alcoholic pancreatitis." (PMID 26734614, 2015). "Therefore, the aim of the present study is to investigate the association of ADH3, ALDH2, and CYP2E1 polymorphisms in alcoholic pancreatitis in North Indian population." (PMID 26734614, 2015).
Autoimmunity (1 paper, 2022). The occurrence of an immune reaction against the organism's own cells or tissues. "Significantly increased serum MDA-protein adducts were revealed using an animal study, which demonstrated CYP2E1-mediated TCE metabolism in autoimmune response and an important role of the Nrf2 pathway in TCE-mediated autoimmunity." (PMID 35736902, 2022).
brain edema (1 paper, 2018). Increased intracellular or extracellular fluid in brain tissue. "Taken together, the present results clearly demonstrated that CYP2E1-mediated metabolism of 1,2-DCE might contribute to oxidative damage in the brain, which, at least in part, underlies the mechanism of 1,2-DCE-induced brain edema." (PMID 30524279, 2018).
Cachexia (1 paper, 2024). Severe weight loss, wasting of muscle, loss of appetite, and general debility related to a chronic disease. "Based on these findings, we propose that ACT may exert its anti-cachexia effects through the regulation of inflammatory response and energy metabolism via multiple targets, including CYP3A4, CYP19A1, CYP2E1, TNF, BCL-2, RYR2, and ATP2A1." (PMID 39872045, 2024).
chronic hepatitis (1 paper, 2020). An active inflammatory process affecting the liver for more than six months. "Our study provides initial experimental evidence to a simmering body of clinical data suggesting that drugs to be important agents in chronic hepatitis, particularly in presence of CYP2E1 inducer." (PMID 32735603, 2020).
colonic adenomas (1 paper, 2005). "Western blot analyses of CYP2E1, CYP3A4, and CYP3A5 were performed with specimens obtained from 25 patients with colonic adenoma and 27 disease-free controls." (PMID 16281975, 2005). "Therefore, the aim of the present study was to determine expression and protein concentrations of four representative CYPs (e.g. CYP2C, CYP2E1, CYP3A4, and CYP3A5) in macroscopically normal colonic tissue of subjects with and without colonic adenomas." (PMID 16281975, 2005).
colorectal adenocarcinoma (1 paper, 2021). The most common type of colorectal carcinoma. "Comparable results were obtained for the model colorectal adenocarcinoma cell line, DLD-1, whose tumorigenesis is also associated with CYP2E1." (PMID 33604316, 2021).
congestive heart failure (1 paper, 2021). Failure of the heart to pump a sufficient amount of blood to meet the needs of the body tissues, resulting in tissue congestion and edema. "In addition, one study showed that inflammatory markers were inversely correlated with CYP1A2 and CYP2C19 activity but not with CYP2D6 and CYP2E1 activity in patients with congestive heart failure." (PMID 34867341, 2021).
craniosynostosis (1 paper, 2025). Craniosynostosis is defined as the premature fusion of one or more cranial sutures leading to secondary distortion of skull shape resulting in skull deformities with a variable presentation. "Furthermore, a single mouse study has found upregulation of Cyp2e1 in calvaria bone tissues of osteogenesis imperfecta mice, but no data on Cyp2e1 and craniosynostosis are present." (PMID 40843495, 2025).
deafness (1 paper, 2020). An inherited or acquired condition characterized by the complete loss of the ability to hear from one or both ears. "Relevant to the symptoms of tinnitus, deletions of the DUSP22 gene in humans results in severe intellectual disability and deafness, while CYP2E1 is integral to the metabolism of acrylonitrile, which has been shown in rodents to potentiate damage to hair cells in the inner ear." (PMID 33192958, 2020).
depression (1 paper, 2019). "It was found that SNS may up-regulate CYP1A2, CYP2D1, CYP2E1, and CYP3A2 activity to reduce IL-6 and TNF-α expression, as well as up-regulation of BDNF and its receptor TrkB, reduce IL-1β, IL-6, and TNF-α expression to treat depression." (PMID 32009949, 2019). "According to the pharmacokinetic parameters, SNS had moderate inhibitory effects in the reserpine-induced depression model on CYP1A2, CYP2D1, CYP2E1, and CYP3A2, but no significant metabolic changes to CYP2C6 and CYP2D2." (PMID 32009949, 2019).
diabetic cardiomyopathy (1 paper, 2022). Diabetic cardiomyopathy is a disorder of the heart muscle in people with diabetes. "The salient findings from the present study support that Cyp1a1, a significantly upregulated DEG, has the highest connectivity in the PPI interaction network among the top five hub genes (Cyp1a1, Cyp2e1, Col1a1, Col3a1, Col1a2) to affect the cardiac function in STZ-induced diabetic cardiomyopathy." (PMID 35387435, 2022).
diabetic nephropathy (1 paper, 2016). "Besides its metabolic role, CYP2E1 gene expression has been associated with the onset of diabetic nephropathy." (PMID 27376033, 2016). "The correlation between CYP2E1 level in peripheral blood lymphocytes and early pathogenesis of diabetic nephropathy has recently been demonstrated." (PMID 27376033, 2016).
edema (1 paper, 2018). An abnormal accumulation of fluid beneath the skin, or in one or more cavities of the body. "This study was designed to explore the role of cytochrome P4502E1 (CYP2E1) expression in the course of brain edema induced by subacute poisoning with 1,2-dichloroethane (1,2-DCE)." (PMID 30524279, 2018).
endometriosis (1 paper, 2021). The growth of functional endometrial tissue in anatomic sites outside the uterine body. "In addition, some identified hub genes of the EC (TAGLN, GATA6, CDH3, CLU, COL8A1, MYH11, MYOCD) and EU (CXCL13, DDK-1, KLF4, CYP2E1, CYP4B1 and PROK1) have been reported be associated with endometriosis." (PMID 34522169, 2021).
endothelial dysfunction (1 paper, 2024). In vascular diseases, endothelial dysfunction is a systemic pathological state of the endothelium (the inner lining of blood vessels) and can be broadly defined as an imbalance between vasodilating and vasoconstricting substances produced by (or acting on) the endothelium. "Furthermore, cytochrome P450 2E1 (CYP2E1) plays a crucial role in alcohol metabolism and increases ROS production, contributing to endothelial dysfunction." (PMID 39194738, 2024).
Fulminant hepatic failure (1 paper, 2021). Hepatic failure refers to the inability of the liver to perform its normal synthetic and metabolic functions, which can result in coagulopathy and alteration in the mental status of a previously healthy individual. "It has been shown that NKT-deficient mice (CD1d-/- and Jα18-/- mice) are more susceptible to fulminant hepatic failure due an marked production of ketone bodies and increased levels of CYP2E1." (PMID 33556084, 2021).
Gla (1 paper, 2023). "Therefore, CYP2E1 may be one of the targets of Gla treatment." (PMID 37432306, 2023).
glaucoma (1 paper, 2023). Increased pressure in the eyeball due to obstruction of the outflow of aqueous humor. "For example, among the drugs for glaucoma treatment, a major cause of legal blindness, these are timolol metabolized by CYP2D6; betaxolol, a substrate for CYP1A2 and CYP2D6; dorzolamide eliminated by CYP2B1, CYP2C9, CYP2E1, and CYP3A2; and pilocarpine, which inhibits CYP2A6, CYP2A13, and CYP2E1." (PMID 36914277, 2023).
Glucose intolerance (1 paper, 2023). Glucose intolerance (GI) can be defined as dysglycemia that comprises both prediabetes and diabetes. "In addition, CYP2E1 inhibition alleviated IR and glucose intolerance in the Ad-USP14 group mice." (PMID 37633951, 2023).
holoprosencephaly (1 paper, 2017). Holoprosencephaly (HPE) is a complex brain malformation resulting from incomplete cleavage of the prosencephalon, occurring between the 18th and 28th day of gestation, and affecting both the forebrain and face, which results in neurological manifestations and facial anomalies of variable severity. "We report here that t-butyl alcohol, which is neither a substrate nor an inhibitor of alcohol dehydrogenases or Cyp2E1, is a potent inducer of holoprosencephaly in Cdon mutant mice." (PMID 28441416, 2017).
intestinal schistosomiasis (1 paper, 2020). An intestinal infection that is caused by Schistosoma japonicum. "The activity of the cytochrome P450 family of enzymes, which include CYP2E1 and CYP7A1, has been reported to be modulated by intestinal schistosomiasis, contingent on granulomatous reactions around the eggs in the tissue." (PMID 32111243, 2020).
ischemia (1 paper, 2021). A hypoperfusion of the BLOOD through an organ or tissue caused by a PATHOLOGIC CONSTRICTION or obstruction of its BLOOD VESSELS, or an absence of BLOOD CIRCULATION. "Another limitation is that knocking CYP2E1 out may interfere with other detoxification mechanisms that may reduce the toxicity of ischemia." (PMID 33466250, 2021).
ischemic stroke (1 paper, 2025). A stroke disorder caused by obstruction of blood flow to the brain, due to thrombotic (local blood clot formation) or embolic (due to a blood clot or other material traveling from another site) event. "A clinical trial involving 121 patients with ischemic stroke reports associations between nucleotide polymorphisms in CYP11B2, CYP2E1, and CYP7A1 and the occurrence of ischemic stroke." (PMID 41249771, 2025).
kidney injury (1 paper, 2021). Trauma to the kidney. "CGA ameliorated oxidative stress and reduced the expression of CYP2E1 in mice with cisplatin-induced kidney injury." (PMID 34836410, 2021).
liver cirrhosis (1 paper, 2022). "In addition, CYP2E1 mediated biotransformation plays a vital role in the formation of macromolecular adducts, which can cause organ damage such as liver cirrhosis." (PMID 35180866, 2022).
liver dysfunction (1 paper, 2025). "CCl4 is metabolised by CYP2E1, and reactive free radicals initiate peroxidation of lipids, especially of polyunsaturated fatty acids, leading to membrane disruption, resulting in cell damage and liver dysfunction." (PMID 40844245, 2025).
liver toxicity (1 paper, 2024). "People with a slow NAT-2 acetylator status and cytochrome P450 2E1 (CYP2E1) polymorphisms are at increased risk for developing INH liver toxicity." (PMID 38628909, 2024).